CTLA4 (cytotoxic T-lymphocyte associated protein 4)
Diseases named in the same sentence as CTLA4 in open-access papers (continued):
Sharing a sentence is not in itself a finding about the gene and the disease.
colitis (continued). "CTLA-4 inhibitors are more associated with colitis, rash, hepatitis, and hypophysitis, while LAG-3 inhibitors are more often associated with colitis, hepatitis, rash, endocrinopathy, and neuropathy." (PMID 38539558, 2024). "CTLA-4 inhibitors generally cause higher irAE rates, such as hypophysitis and colitis, whereas PD-1/PD-L1 inhibitors are more often linked to pneumonitis and myocarditis." (PMID 39682118, 2024). "Accordingly, insufficient expression of other regulatory immune checkpoint molecules, such as CTLA-4, or inactivation of their regulatory function by checkpoint inhibitors can cause colitis." (PMID 38363399, 2024). "For instance, CTLA-4 inhibitors were associated with a higher incidence of colitis and diarrhea, while PD-1 inhibitors showed a strong trend toward immune-related AEs, again, congruent with the current literature." (PMID 39051335, 2024). "CTLA-4 inhibitors predominantly resulted in diarrhea and colitis, with ipilimumab frequently causing pyrexia and rash, while tremelimumab exhibited unique AEs such as biliary tract infection." (PMID 39051335, 2024). "Pneumonitis and thyroiditis are more prevalent in anti-PD-1 therapy, while hypophysitis and colitis are more commonly associated with anti-CTLA-4 therapy." (PMID 39061225, 2024). "The most common cause of death from anti‐CTLA‐4 was colitis (70%), whereas pneumonia (35%), hepatitis (22%), and neurological toxicities (15%) were the main causes of death from anti‐PD‐1/PD‐L1." (PMID 38967259, 2024). "Myocarditis and colitis are the most prevalent causes of death resulting from combination therapy (e.g., anti-PD-1/CTLA-4)." (PMID 38165484, 2024). "Among these, irAE-induced colitis has been reported in approximately 5.7–9.1% of patients treated with anti-cytotoxic T-lymphocyte associated protein 4 (CTLA-4) antibodies and 0.7–1.6% of patients with anti-programmed cell death protein 1 (PD-1) antibodies." (PMID 38965595, 2024). "In the retrospective study by Abu-Sbeih and colleagues, it was suggested using a univariable analysis that the only risk factor for development of ICI colitis was the use of CTLA-4, and there was a trend toward IBD involvement of the colon." (PMID 36765649, 2023). "CTLA-4 inhibitors often cause colitis, hypophysitis, and rash, while PD-1/PD-L1 inhibitors often cause pneumonia and thyroid dysfunction." (PMID 37304306, 2023). "Their study focused on how mechanistic differences between cytotoxic T-lymphocyte antigen-4 (CTLA-4) and programmed death-1 (PD-1) affect colitis, by mapping the FAERS data to the associated molecular pathway and target levels." (PMID 37376121, 2023). "Mucosal TNF levels are high in patients with anti-CTLA-4 therapy-induced colitis, with lower levels of TNF associated with response to steroids." (PMID 36776862, 2023). "Skin rash onsets at the earliest, while diarrhea and/or colitis are the most frequent irAEs caused due to the administration of anti-CTLA-4 antibodies." (PMID 37445336, 2023). "The PRR indicating the statistical association between a drug and colitis was ~3 times higher for ipilimumab (the anti-CTLA-4 drug), compared to the PRRs for nivolumab and pembrolizumab (anti-PD-1 drugs)." (PMID 37376121, 2023). "Second, our analysis was focused on ipilimumab-based immunotherapy, since colitis has been mainly associated with anti-CTLA-4 agents, occurring in 10–20% of patients undergoing this type of treatment." (PMID 37452874, 2023). "Compared to PD-1/PD-L1 inhibitors, CTLA4-inhibitors frequently cause colitis (irAE-GI), hypophysitis, and dermatitis (irAE-skin), and less frequently, cause pneumonitis (irAE-lung), hypothyroidism, and skeletal symptoms such as myalgias and arthralgias." (PMID 35558065, 2022). "Immune checkpoint inhibitor (ICI)-induced colitis is one of the known complications of therapies targeting cytotoxic programmed cell death protein 1 (PD-1), cytotoxic T lymphocyte-associated antigen 4 (CTLA-4), and programmed cell death ligand 1 (PD-L1)." (PMID 35814408, 2022).
colitis (continued). "Colitis caused by CTLA-4 inhibitors appears to occur later than that caused by PD-1/PD-L1 inhibitors, with a median onset time of about 6 to 7 weeks." (PMID 36189293, 2022). "In a mouse study, anti-CTLA-4 treatment was combined with DSS administration to model severe ICI-associated colitis." (PMID 36713364, 2022). "The proposed mechanism was through higher expression CTLA-4 on Tregs thereby causing their inhibition while consequently inducing effector T cell activation, resulting in both antitumor effects and colitis (an immune related adverse event)." (PMID 35474500, 2022). "Combination PD-1/ cytotoxic T-lymphocyte-associated protein 4 (CTLA-4) deaths were frequently from colitis (32 [37%]) and myocarditis (22 [25%])." (PMID 35300724, 2022). "Overall, the prevalence and severity of colitis caused by CTLA-4 inhibitors are higher than those caused by PD-1/PD-L1 inhibitors." (PMID 36189293, 2022). "IrAE colitis is strongly associated with anti-CTLA-4 treatment, with 8-22% of patients developing any grade of irAE colitis." (PMID 35936135, 2022). "For instance, poor responses to the inhibition of CTLA-4 by ipilimumab, as well as increased side effects (such as mucosal damage and colitis), were associated with a decrease in Bacteroides species in the intestines." (PMID 36142843, 2022). "The most frequent cause of fatal events with CTLA-4 inhibitors was colitis, while pneumonitis, hepatitis, and neurotoxic adverse effects were most likely associated with fatal events with PD-1/PD-L1 inhibitors." (PMID 35621642, 2022). "Mice treated with B. fragilis and Burkholderia cepacia reduced symptoms of colitis caused by CTLA-4 inhibitors and enhanced the therapeutic effect." (PMID 36189293, 2022). "The deficiency of CTLA-4 leads to severe autoimmune diseases (colitis and myocarditis) characterized by T-cell infiltration in murine models." (PMID 35774996, 2022). "In a large retrospective review, the most common cause of fatal irAEs was myocarditis and colitis with anti-CTLA-4 agents and pneumonitis with anti-PD-1/PD-L1 agents." (PMID 35621642, 2022). "Single-cell analysis of ICI-associated colitis patient samples found expansion of CTLA-4+ Treg cells and differentiation of CD8 Trm cells to cytotoxic effector cells." (PMID 35432346, 2022). "Although Ipilimumab, a monoclonal antibody to CTLA-4, is highly effective in immunotherapy, it can sometimes cause colitis." (PMID 34357126, 2021). "We demonstrate similar findings in both anti–CTLA-4/PD-1 combination therapy and in anti–PD-1 inhibitor-associated colitis." (PMID 34147519, 2021). "We previously demonstrated that anti–CTLA-4/PD-1 colitis is associated with high levels of activated (HLA-DR+CD38+) memory CD8+ T cells, and lower proportions of regulatory T cells compared with UC." (PMID 34147519, 2021). "Firmicutes genera, enriched in the baseline gut microbiome of LC patients, has been previously associated with development of CTLA-4 mediated colitis." (PMID 34256732, 2021). "Other toxicities included arthritis grade 3 (n = 2) and colitis grade 2 (n = 1), associated with single-agent anti-PD1 and colitis grade ≥2 (n = 8), associated with anti-CTLA4." (PMID 34208218, 2021). "These include T regulatory cell defects such as IPEX syndrome and CTLA4 deficiency and immune dysregulation with colitis." (PMID 34226669, 2021). "The risk of developing grade III–IV checkpoint inhibitor colitis (CIC) in patients receiving CTLA-4 inhibitors, PD-1/PD-L1 inhibitors, or the combination is 8%, 1–2%, and 11%, respectively." (PMID 34338882, 2021). "There are many immune-related adverse events caused by the anti-CTLA-4 antibodies, including colitis and inflammatory bowel disease." (PMID 34203292, 2021). "The risk of colitis was higher in patients treated with anti-CTLA-4 antibodies than in those treated with anti-PD-1 (ROR025 2.6) or anti-PD-L1 antibodies (ROR025 4.8)." (PMID 34912213, 2021).
colitis (continued). "It was shown that having more bacteria from the Bacteroidetes phylum protected from colitis in CTLA-4 therapy, whereas Faecalibacterium raised the risk of ipilimumab treatment-associated colitis." (PMID 34360795, 2021). "Research showed that patients with a higher level of Faecalibacterium prausnitzii and other related Firmicutes, and with a lower level of Bacteroidetes, had a higher risk of colitis caused by the anti-CTLA-4 therapy." (PMID 34203292, 2021). "In humans, ICI-associated colitis is more common during CTLA-4 blockade than during PD-1/PD-L1 blockade." (PMID 34162429, 2021). "Colitis induced by CTLA-4 inhibitors seemed to happen later than that caused by PD-1/PD-L1 inhibitors." (PMID 34992611, 2021). "Combination treatment with both anti-CTLA-4 and anti-PD-1 carry the highest risk of adverse effects, particularly colitis, and often affected multiple organs." (PMID 34694371, 2021). "Since most patients in our study received anti-PD1/PD-L1 monotherapy, irAEs that are most commonly associated with anti-CTLA4 therapy or its combinations thereof, such as colitis, and diarrhea were rare." (PMID 34823493, 2021). "Recent data utilized single-cell technology to identify cytotoxic CD8+ T cells as the main pathogenic gastrointestinal population in anti–CTLA-4/PD-1 colitis." (PMID 34147519, 2021). "The risk of developing colitis was more than three times higher with anti-CTLA-4 therapy than with PD-1/PD-L1 inhibitors (OR 3.12; 95% CI 1.06–9.24)." (PMID 33923423, 2021). "And the variables associated with a higher recurrence rate of irAEs were anti-CTLA-4 regimen, age, colitis, hepatitis, and pneumonia, in order." (PMID 34458371, 2021). "TNF also mediates colitis caused by immune checkpoint blockade with anti–CTLA-4 and anti–PD-1 antibodies." (PMID 34101617, 2021). "According to related studies, there was a higher risk of colitis in patients with a higher abundance of Faecalibacterium prausnitzii and a lower abundance of Bacteroides after anti-CTLA-4 treatment." (PMID 34568308, 2021). "Mice knocked out CTLA-4 presented diffuse immune cells infiltration in various organs and fatal colitis caused by increased T-cell activity." (PMID 34992611, 2021). "Our data reveals the fundamental mechanism underlying trafficking-blocking antibody therapy for CTLA-4 blockade-induced colitis and provide a caution in regard to apply trafficking-blocking antibody treatment under CTLA-4 blockade condition." (PMID 32183814, 2020). "In an analysis of 193 fatal ICPI-related toxic events caused by anti-CTLA-4 antibodies, 135 event (~ 70%) fatalities were related to colitis." (PMID 32183814, 2020). "Particularly, colitis has been associated with anti-CTLA4, whereas pneumonitis has been related to anti-PD1 treatment, as shown in our study." (PMID 33064239, 2020). "These affirm the accurately predicted value of the intestinal bacterial spectrum and genome as potential biomarkers for identifying patients who are at risk of developing CTLA-4-related colitis." (PMID 33123120, 2020). "Although rarely lethal, colitis has been reported as the first cause of treatment-related death in patients under anti-CTLA4 therapy." (PMID 33064239, 2020). "Combination therapy with CTLA-4 and PD-1 inhibitors is associated with a significantly higher incidence and severity of irAEs (including colitis) than single-agent PD-1 inhibition." (PMID 32418993, 2020). "Specifically, all grades colitis, hypophysis, and rash were more common with CTLA-4 inhibitors, whereas PD-1 inhibitors had increased risk for development of pneumonitis, hypothyroidism, arthralgia, and vitiligo." (PMID 33123120, 2020). "While the monoclonal antibody against CTLA-4 is effective, ipilimumab can cause subclinical colitis." (PMID 31293523, 2019). "Severe colitis has been reported in approximately 5% of patients treated with cytotoxic T-lymphocyte-associated antigen-4 (CTLA-4) inhibitors, such as ipilimumab." (PMID 31428491, 2019).
colitis (continued). "Based on stool samples collected from patients treated with an anti-CTLA-4 antibody, bacteria in the Bacteroidetes phylum were associated with lower incidence of treatment-induced colitis." (PMID 30995949, 2019). "When PD-1 inhibitors were compared directly with CTLA-4 inhibitors, the relative risk of all-grade diarrhea and colitis was 0.58 and 0.16, respectively." (PMID 31293970, 2019). "Incidence of anti-PD-1/PD-L1 perforating colitis is less frequent compared to anti-CTLA-4 treatment-associated perforated colitis." (PMID 31708780, 2019). "Additional studies revealed that patients with low abundance of Bacteroidetes and elevated Faecalibacterium prausnitzii and other related Firmicutes harbored an elevated risk of colitis in anti-CTLA-4 therapy." (PMID 30158926, 2018). "An analysis of the intestinal microbiome in patients taking anti-CTLA-4 therapy revealed that abundance of the Bacteriodetes phylum was associated with resistance to colitis." (PMID 30263059, 2018). "The immune-related adverse effects associated with these treatments such as diarrhea, colitis, and CTLA-4 treatment-associated perforating colitis have been reported." (PMID 29955400, 2018). "Gastrointestinal immune-related adverse events are commonly associated with anti-CTLA-4 therapy, and colitis tends to be the first immune-related adverse event leading to discontinuation of anti-CTLA-47,10." (PMID 30228268, 2018). "Here the authors show that lower abundance of Bacteroidetes and vitamin B biosynthetic modules in fecal samples of melanoma patients can predict their susceptibility to colitis following anti-CTLA-4 treatment." (PMID 26837003, 2016). "Our study is the first to characterize the intestinal microbiota of patients before the development of intestinal inflammation and has identified microbiota-associated biomarkers that correlate with protection against CTLA-4 blockade-associated colitis." (PMID 26837003, 2016). "In clinical trials, treatment with anti-CTLA4 has been associated with multiple immune-related adverse events including colitis, hepatitis, and thyroiditis." (PMID 25614821, 2015). "Other studies have demonstrated that anti-CTLA-4 in animal models led to T-cell-associated autoimmune toxicities, including diabetes, demyelinating lesions, encephalomyelitis and colitis." (PMID 24594636, 2014). "CTLA-4 blockade with ipilimumab can cause dysregulation of GI mucosal immunity that results in irAEs such as diarrhea and colitis, or events that involve the esophagus, duodenum, ileum, and stomach." (PMID 24278787, 2013). "Pembrolizumab-induced colitis, though less frequent than with cytotoxic T-lymphocyte-associated protein 4 (CTLA-4) inhibitors, can range in severity from mild to life-threatening, necessitating prompt recognition and management to prevent severe outcomes such as bowel perforation or even death." (PMID 41523718, 2026). "Similarly, lower levels of IL-6, IL-8, and sCD25 were associated with the development of anti-CTLA-4-induced colitis, as demonstrated using multiplex assays." (PMID 40632185, 2025). "In multiple myeloma, CTLA-4 inhibitors enhance effector T cell function by blocking early T cell activation signals, but this is associated with severe immune-related toxicities (such as colitis and hepatitis)." (PMID 41479783, 2025). "In addition, other reports have suggested that PD‐1/PD‐L1 antibodies (and other similar drugs, including CTLA‐4 antibodies) can cause gastritis, enteritis, and colitis, and the histological findings vary depending on the drug." (PMID 39749301, 2025). "Other studies have underlined how certain changes in the intestinal microbiota may predispose to colitis associated with anti-CTLA4 and/or anti-PD1 therapy." (PMID 39934899, 2025).
colitis (continued). "Genetic deletion of Ctla4 in the innate immune compartment triggered a pro-inflammatory transcriptional program in the colon and predisposed to more severe innate-immune mediated colitis, confirming that CTLA-4 curtails ILC-mediated mucosal inflammation." (PMID 39496592, 2024). "This could be attributed to the addition of the CTLA-4 inhibitor, as it is more frequently linked to colitis and less so to pneumonitis." (PMID 38248113, 2024). "Notably, ICIs targeting cytotoxic T-lymphocyte associated protein-4 (CTLA-4) are more likely to cause colitis compared to those targeting programmed cell death protein-1 (PD-1) and programmed cell death-ligand 1 (PD-L1)." (PMID 39336463, 2024). "There may be a difference in the risk of colitis between PD-1/L1 inhibitors and CTLA-4 inhibitors, suggesting that CTLA-4 more thoroughly inhibits T cell activation." (PMID 38660314, 2024). "Additionally, the type of tumor and treatment seems to be involved, since colitis and skin irAEs are generally more common in patients with underlying melanoma who are treated with anti-CTLA-4 therapy." (PMID 37511260, 2023). "By contrast, Bacillota members, including Lachnospiraceae, Faecalibacterium spp., Streptococcus spp., and Intestinibacter bartlettii, have been associated with ICI colitis and other irAEs in independent cohorts of anti-CTLA-4, anti-PD-1, or combination ICI-treated metastatic melanoma patients." (PMID 36622383, 2023). "Notably, studies have reported diarrhea in 27%-54% of cancer patients undergoing cytotoxic T-lymphocyte-associated antigen-4 (CTLA-4) inhibitor therapy, while colitis occurred in 8%-22% of these patients." (PMID 37378156, 2023). "The risk of colitis recurrence was increased if patients had a longer duration of symptoms and required immune-suppression for initial colitis, whereas resumption of anti–PD-1/L1 led to lower risk than resumption of anti–CTLA-4." (PMID 38090496, 2023). "Aside from the most common constitutional symptoms, such as fever, pruritus and fatigue, anti-CTLA-4 is more associated with diarrhea (36%), colitis (8%) and hypophysitis (4%), while anti PD-1 and PD-L1 can lead more frequently to thyroiditis (8%) and pneumonitis (4%)." (PMID 37511260, 2023). "Colitis, hypophysitis, and rash are frequently associated with CTLA4 inhibitors." (PMID 35558065, 2022). "Regulatory T-cells express high levels of CTLA-4, and therefore may be inactivated by ipilimumab and allow effector T cell activation, causing both tumour response and colitis." (PMID 35046403, 2022). "Rikenellaceae were correlated with resistance to the development of colitis after CTLA-4 (cytotoxic T lymphocyte-associated antigen 4) blockade and could limit inflammation by stimulating T-regulatory cell differentiation." (PMID 33097510, 2021). "With ipilimumab (anti-CTLA-4) monotherapy, the most common adverse effect is colitis, whereas nivolumab and pembrolizumab (anti-PD-1) have been found to cause hypothyroidism, rash, and diarrhoea (more commonly than colitis)." (PMID 34694371, 2021). "They found that the death of patients treated with anti-PD-1 and anti-CTLA-4 antibodies was usually caused by colitis [32 (37.0%)] and myocarditis [22 (25.0%)], and the fatal toxic effects usually occurred early after therapy initiation for combination therapy." (PMID 33413213, 2021). "The Mediterranean diet must be researched further, in order to determine its influence on the Firmicutes levels, which could affect the immunotherapy’s effectiveness, due to its connection with a higher risk of colitis caused by CTLA-4 therapy." (PMID 34203292, 2021). "Similar to colitis, the risk of hepatobiliary disorders in the anti-CTLA-4 antibodies group was speculated to be higher than PD-1/PD-L1 inhibitors (ROR025 1.3 and 1.3, respectively)." (PMID 34912213, 2021).